SOX11 (SRY-box transcription factor 11)
Diseases named in the same sentence as SOX11 in open-access papers (continued):
Sharing a sentence is not in itself a finding about the gene and the disease.
gastric cancer (continued). "As in vitro and in vivo cell model analyses strongly suggested a tumor-suppressor role of SOX11 in gastric cancer cells, we asked whether the expression pattern of SOX11 human gastric cancer tissues agreed with the cell study." (PMID 24604109, 2014). "The expression of SOX11 in human gastric cancer was examined by immunohistochemistry." (PMID 24604109, 2014). "We investigated the role of SOX11 overexpression on gastric cancer malignant behavior." (PMID 24604109, 2014). "In this study, we examined the role of SOX11 in gastric cancer using in vitro and in vivo models." (PMID 24604109, 2014). "However, the function of SOX11 in gastric cancer is unclear." (PMID 24604109, 2014). "We next asked whether overexpression of SOX11 affected gastric cancer migration and invasion." (PMID 24604109, 2014). "Furthermore, SOX11 expression was correlated with improved survival in gastric cancer patients." (PMID 24604109, 2014). "On the other hand, abnormal methylation of genes, for example, IGF2, SLC16A2, SOX11, P2RX7, and MYOD1, were identified in H. pylori infection and significantly correlated with gastric cancer and its clinicopathological features." (PMID 41614769, 2025). "What’s more, our team has been worked on some of the differential genes such as PHF10, CEACAM6, SFRP1, SOX11, CLDN1 to investigate their expression and functions in gastric cancer and the results perfect proved our microarray data." (PMID 25928635, 2015). "It has also been reported that the overexpression of SOX11 strongly suppresses cell migration/invasion in vitro and in vivo but does not inhibit cell proliferation in gastric cancer." (PMID 26578390, 2015). "Notably, five gastric cancer cell lines (NCI-N87, Hs746T, AGS, KATO-III) showed higher and five cell lines (MKN28, BGC823, SGC-7901, SNU1, SNU16) showed lower SOX11 protein levels." (PMID 24604109, 2014). "However, we showed that SOX11 levels did not affect gastric cancer cell growth." (PMID 24604109, 2014). "We found that SOX11 overexpression did not suppress the growth of SGC-7901 and MKN45 (data not shown) gastric cancer cells in soft agar and Matrigel." (PMID 24604109, 2014).
melanoma (9 papers, 2016 to 2025). A malignant, usually aggressive tumor composed of atypical, neoplastic melanocytes. "Transcripts related to melanoma progression and poor prognosis (Sox6, Sox11, Tfap2a, Myo7a) were upregulated in IgG-treated animals." (PMID 38740748, 2024). "Circos plots further showed that hsa-miR-122-5p, which was profoundly upregulated in our metastatic UM samples, is implicated in stemness of cells and melanoma development by targeting Nodal growth differentiation factor (NODAL), SOX11, WNT11 and CDK4." (PMID 36619870, 2022). "This study aimed to investigate the diagnostic and prognostic utility of the conventional pan-melanoma cocktail members (HMB-45, melan-A and tyrosinase), in conjunction with SOX10 and SOX11 immunohistochemical (IHC) expression." (PMID 33801642, 2021). "Reactivity of SOX-11 in melanoma has rarely been reported in the literature before, although neuroectodermal differentiation may be seen occasionally." (PMID 39258061, 2024). "Triple SOX10/SOX11/MITF positivity might serve as a diagnostic tool for conventional pan-melanoma cocktail negative cases." (PMID 33801642, 2021). "The Venn diagram outlined that 37.14% of the 105 MMs (n = 39) displayed positivity for all the examined markers: S100, SOX10, SOX11, MITF, and conventional pan-melanoma cocktail." (PMID 33801642, 2021). "The 15 negative conventional pan-melanoma-cocktail cases were represented by 9 cases with SOX11/SOX10/MITF triple positivity, 4 cases expressing only SOX10 positivity, and 2 cases that expressed HMB-45 and melan-A." (PMID 33801642, 2021). "Triple MITF/SOX10/SOX11 co-expression was seen in 9 out of 15 negative conventional pan-melanoma-cocktail cases." (PMID 33801642, 2021). "If SOX10/SOX11 double positivity might serve as an indicator of lymphatic invasion, triple SOX11/SOX10/MITF gene interaction might induce genesis of a subtype of MMs which do not express positivity for the conventional pan-melanoma cocktail." (PMID 33801642, 2021). "The independent prognostic value was proved for the conventional pan-melanoma cocktail (triple positivity for HMB-45, melan-A, and tyrosinase) and, independently for HMB-45 and tyrosinase, but not for melan-A, SOX10, or SOX11." (PMID 33801642, 2021). "This set of genes included forkhead box C1 (FOXC1), keratin 14 (KRT14), cyclin E1 (CCNE1), melanoma inhibitory activity (MIA) and secreted frizzled-related protein 1 (SFRP1), while expression of CDCA1 and MELK, (neither of which were detectable in MCF7), did not change following SOX11 depletion." (PMID 26894864, 2016).
osteoarthritis (9 papers, 2008 to 2023). A noninflammatory degenerative joint disease occurring chiefly in older persons, characterized by degeneration of the articular cartilage, hypertrophy of bone at the margins and changes in the synovial membrane. "For instance, SOX11 was reported to be upregulated in both patients with OA and IL-1β-treated chondrocytes, which was associated with osteoarthritis progression via the induction of TNF-α." (PMID 36835620, 2023). "The dysregulation of SOX11 has been implicated in a number of diseases, including neurodevelopmental disorders and osteoarthritis, and a wide variety of cancers." (PMID 36768267, 2023). "Several transcription factors have been implicated in the onset and progression of osteoarthritis, including Runx2, C/EBPβ, HIF2α, Sox4, and Sox11." (PMID 32079226, 2020). "Furthermore, expression of SOX4 and SOX11 was associated with the destruction of cartilage in patients with osteoarthritis, suggesting the importance of these transcription factors in both the onset and progression of osteoarthritis." (PMID 32079226, 2020). "Unlike SOX4, which is upregulated in almost all of the studies investigating its role in arthritis disease, SOX11 is downregulated in some studies and upregulated in others during osteoarthritis progression." (PMID 36835620, 2023). "In a model of IL-1β-induced murine osteoarthritis, SOX11 was significantly down-regulated by IL-1β in chondrocytes, whereas TsI treatment reversed this down-regulation and protected chondrocytes from IL-1β-induced apoptosis." (PMID 37391758, 2023). "Immunohistochemical analysis revealed that SOX11 expression was decreased from early stages of osteoarthritis progression, as assessed by decreased Safranin-O staining and modified Mankin’s cartilage degradation scores." (PMID 23356643, 2013). "To know the role of SOX11 in cartilage homeostasis, we next created an experimental osteoarthritis (OA) model through surgical induction of instability in the knee joints of 8-week-old mice." (PMID 23356643, 2013). "To explore the roles of Sox11 in joint homeostasis, we analyzed adult knee joints in an osteoarthritis mouse model where the medial meniscus and the medial collateral ligament were removed." (PMID 23356643, 2013). "In addition, SOX11 protein was shown to be expressed in the articular cartilage of healthy mature mice, but its level decreased in the cartilage of osteoarthritis mouse models." (PMID 36835620, 2023). "Ingenuity Pathway Analysis identified SOX11, involved in osteoarthritis pathway and differentiation of osteoblasts, together with miR-204-5p, a potential upstream regulator, suggesting the critical role of miR-204-5p-SOX11 regulation in the aging process of human bones." (PMID 29371932, 2017). "Finally, to investigate the roles of SOX11 in joint homeostasis, we examined its expression pattern in an osteoarthritis experimental model of knee joints in adult mice and human samples after total knee replacement surgery." (PMID 23356643, 2013). "In addition we detected novel proteins that were deregulated in osteoarthritis, such as SOX11, FGF23, KLF6, WWOX and GDF15." (PMID 19011694, 2008). "Finally, we find that SOX11 protein levels are decreased in degraded cartilage during osteoarthritic progression in humans and mice, indicating a possible role of SOX11 in pathogenesis of osteoarthritis." (PMID 23356643, 2013). "So MIAT knockdown alleviates LPS-induced chondrocytes inflammatory injury via regulating miR-488-3p/SOX11 axis through NF-κB signaling pathway and regulating TLR4 expression in osteoarthritis." (PMID 34124371, 2021). "This work implicates SOX11 as a potential regulator of GDF5 expression in joint maintenance and suggests a possible role in the pathogenesis of osteoarthritis." (PMID 23356643, 2013). "Proteins such as SOX11, FGF23, KLF6, WWOX and GDF15 not implicated previously in the genesis of osteoarthritis were identified." (PMID 19011694, 2008).
glioblastoma (8 papers, 2020 to 2024). The most malignant astrocytic tumor (WHO grade IV). "The transcription factor SOX11 is a tumor-associated antigen with low expression in normal cells, but overexpression in glioblastoma (GBM)." (PMID 36768267, 2023). "In our preceding study, we elucidated the capability of NGN2 and SOX11 to transform glioblastoma cells into neurons, resulting in cell cycle arrest." (PMID 39390804, 2024). "Although it alone can induce differentiation of glioma stem‐like cells, NGN2 requires SOX4 or SOX11 for highly efficient neuronal reprogramming of human glioblastoma cells." (PMID 39390804, 2024). "In this study, we examined the molecular mechanism by which SOX4 or SOX11 enables NGN2 to highly efficiently reprogram human glioblastoma cells into neurons." (PMID 39390804, 2024). "We observed a consistent positivity for SOX11 in the IDH1mt subset of diffuse gliomas (n = 34), and IDH1mt tumours showed significantly higher expression of SOX11 when compared to glioblastomas (median mHS 2 vs. 25.8, p < 0.001, MW)." (PMID 37568909, 2023). "Furthermore, gene expression of four tested GSC markers (CD133, SOX11, ALDH1A3, S100A4) was markedly reduced upon REST loss compared with wild-type glioblastoma cells." (PMID 38609948, 2024). "In our study, human SOX4 and SOX11 either could highly efficient (95%) reprogramming U251 cell into neuron cell, which is a promising strategy for glioblastoma therapy." (PMID 39390804, 2024). "Accumulated evidence indicates that several SOX members have been identified as tumor-specific antigens that can augment cytotoxic T lymphocytes (CTLs) response to kill cancer cells, including SOX2 (glioblastoma), SOX4 (lung cancer), SOX6 (glioblastoma), and SOX11 (glioblastoma)." (PMID 35267473, 2022). "Our results indicate that immunohistochemical detection of EGFR, MEOX2, SOX11, and INSM1 can be useful for detection of glioblastoma cells in limited histological samples, especially when used in combination." (PMID 37568909, 2023). "Compared to IDH1-mutant tumours, glioblastomas showed significantly higher expression of EGFR, MEOX2, and CD34 and significantly lower positivity for SOX11." (PMID 37568909, 2023). "While either SOX11 or ZIC1 promotes the expression of TUBB3/βIII-tubulin and induces a neuronal phenotype in U87 glioblastoma cells, the expression of ZIC1 greatly enhances the impact SOX11 has on TUBB3 expression and neuronal differentiation." (PMID 35573698, 2022).
hepatocellular carcinoma (8 papers, 2019 to 2023). A malignant tumor that arises from hepatocytes. "Experiments confirmed that SOX11 is a target for miRNA-182, and a decrease in miRNA-182 inhibits the growth of hepatocellular carcinoma cells and downregulates BCL2 expression." (PMID 37894763, 2023). "GABBPA inhibits metastasis of hepatocellular carcinoma and SOX11 is important in the regulation of hepatocellular carcinoma cell proliferation, migration and invasion." (PMID 30967126, 2019). "It has also been shown that SOX11 may be associated with specific key pathways related to certain developmental processes, including the WNT signaling pathway and the TCF/β-linked protein complex in hepatocellular carcinoma." (PMID 36551589, 2022). "miR-9-5p enhances the tumorigenic ability of hepatocellular carcinoma cells by targeting CPEB3 and ESR1, but miR-9 plays a tumor suppressor role in hepatocellular carcinoma by regulating IGF2BP1, Sox11, and P21." (PMID 36421826, 2022). "As for hepatocellular carcinoma cell line (E118), E2F8, GABBPA and SOX11 were recovered." (PMID 30967126, 2019).
leukemia (8 papers, 2019 to 2025). A malignant (clonal) hematologic disorder, involving hematopoietic stem cells and characterized by the presence of primitive or atypical myeloid or lymphoid cells in the bone marrow and the blood. "The majority of MCL cases express the transcription factor SOX11: the rare SOX11-negative cases have a more indolent course, more frequent leukemia transformation, less nodal involvement, and the probability of progression is lower." (PMID 38534887, 2024). "The function of SOX11 in leukemias and its clinical significance as a biomarker were further explored." (PMID 32029838, 2020). "Among the negatively associated genes, several genes including PAX2, IL2RA, SOX11, and PAK7 played as oncogenes in leukemia." (PMID 32209730, 2020). "Taken together, SOX11 knockdown leads to alterations in genes and cellular processes related to leukemia cell motility, adhesion, differentiation, and drug response." (PMID 32029838, 2020). "Studies have shown that SOX11-negative MCL is linked to a higher incidence of leukemia without lymph node involvement, classic histological morphology, and a lower Ki-67 index." (PMID 35992854, 2022). "We next investigated the biology behind the increased SOX11 expression in leukemia." (PMID 32029838, 2020). "We also tested whether a methyltransferase inhibitor, decitabine, could reverse SOX11 expression in leukemia cell lines." (PMID 32029838, 2020). "Interestingly, MDK, which is involved in cell migration and growth, was downregulated by SOX11 knockdown in leukemia cell lines here and in an MCL cell line Z13816." (PMID 32029838, 2020). "Cell viability and proliferation assays did not demonstrate any significant changes, and SOX11 knockdown did not have any impact on sensitivity to known leukemia drugs, such as dexamethasone, prednisolone, vincristine, and asparaginase." (PMID 32029838, 2020). "Further immunostaining was negative for cyclin-D1 and SOX11 and positive for CD43 and LEF1, overall consistent with CLL/SLL-induced subcutaneous leukemia cutis." (PMID 40893576, 2025).
lung carcinoma (8 papers, 2012 to 2022). "We found that SOX11 mutations were most seen in esophageal, gastric and lung cancers, while SOX11 amplification was most commonly seen in liver cancer." (PMID 36551589, 2022). "SOX11 mutations were reported to occur frequently in the hotspot(D233 del/2_D233 del) in esophageal, gastric and lung cancers, while amplification was the major form of genetic alteration in neuroendocrine prostate cancer (NEPC), OV, PRAD, BRCA and UCEC." (PMID 36551589, 2022). "Mutations in SOX11 frequently occurred in esophageal, stomach, and lung cancers with D233 del/2_D233 del hotspot." (PMID 34442467, 2021). "Next we examined the expression of SOX11 in normal lung tissue and different types of lung cancers, which is compared with the expression of INSM1, SYN, CGA and CD56." (PMID 34996493, 2022). "For example, the mitochondrial protein TMEM65 is amplified and overexpressed in ~50% of BM from breast and lung cancers, SOX11 is amplified and overexpressed in ~30% of breast and ~80% of lung cancer-BM, and NRG1 is lost and suppressed in ~60% of BCBM." (PMID 28098771, 2017). "However, there are very few studies on the expression and significance of SOX11 in lung cancer." (PMID 35033084, 2022).
malignant glioma (8 papers, 2007 to 2024). A grade III or grade IV glioma arising from the central nervous system. "Overexpression of SOX-11 can be seen in malignant gliomas and tumors with primitive neuroectodermal differentiation." (PMID 39258061, 2024). "Previously, we and others have reported that the combined transcription factors (BRN2/ASCL1/ MYT1L or NGN2/SOX11) could reprogram human malignant glioma cells into terminally differentiated neuron-like cells and successfully impede brain tumor development." (PMID 31212628, 2019). "Our previous study also identified that NGN2 and SOX11 (sex-determining region Y-box 11) could cooperatively reprogram malignant glioma cells into postmitotic neuron-like cells, leading to significant inhibition of tumor growth." (PMID 31212628, 2019). "In addition, highly specific overexpression of the transcription factor SOX11 has been detected in human malignant gliomas." (PMID 23658834, 2013). "To test this hypothesis, we infected human malignant glioma cells, U251 and U87, with lentivirus-expressing NGN2-IRES-GFP-T2A-SOX11 (NGN2/SOX11)." (PMID 25321470, 2014).
Coffin–Siris syndrome 9 (7 papers, 2021 to 2025). "SOX11 was associated with Coffin–Siris syndrome 9, commonly with dysmorphic facial features." (PMID 36672963, 2023). "Coffin-Siris syndrome 9 (CSS9), a rare congenital disorder caused by SRY-related HMG-box 11 gene (SOX11) deficiency, is characterized by high phenotypic heterogeneity including a wide spectrum of organ anomalies." (PMID 40933692, 2025). "We also demonstrate that TRIP12 is closely related to the Coffin–Siris syndrome 9 (CSS9) episignature, which is the result of variants in SOX11." (PMID 36430143, 2022). "A tree-and-leaf plot showed that the JARID2 genome-wide DNA methylation change is most closely related to the DNA methylation changes of Coffin–Siris syndrome-9 (CSS9; SOX11), myopathy, lactic acidosis, and sideroblastic anemia 2 (MLASA2; YARS2) and Lysine-demethylase 2B (KDM2B)." (PMID 37762546, 2023).
chronic lymphocytic leukemia (6 papers, 2016 to 2024). "And the high expression of SOX11 was strongly associated with poor prognostic factors of chronic lymphocytic leukemia (CLL)." (PMID 36551589, 2022). "In contrast to follicular lymphoma, small lymphocytic lymphoma and reactive lymphoid tissue, most MCLs (48/53 patients) in a study expressed SOX11 protein in the nucleus." (PMID 26949534, 2016). "Atypical chronic lymphocytic leukemia (CLL) and small lymphocytic lymphoma (SLL) may also demonstrate positive for cyclin D1 but do not have CCND1 translocations and usually lack SOX-11 expression." (PMID 34442137, 2021).
colon cancer (6 papers, 2014 to 2024). "Among these, SOX11 has a cancer-suppressive effect on a variety of cancers, inhibits the migration of colon cancer cells, and excessive SOX11 alleviates HCC progression." (PMID 38084140, 2023). "In order to explore the function of miR‐223‐3p in colon cancer, qPCR and western blot were conducted to confirm the regulation of SOX11 in both cells with miR‐223‐3p mimic or inhibitor treatment." (PMID 32045135, 2020). "PcDNA3.1‐SOX11 was transfected into TH29 and SW480 cells to determine the effect of SOX11 on colon cancer cells." (PMID 32045135, 2020). "Our study confirmed that LINC00961 suppressed the migration and invasion of colon cancer cells through the miR‐223‐3p/SOX11 axis." (PMID 32045135, 2020). "Overexpression of SOX11 can inhibit the invasion of colon cancer." (PMID 35033084, 2022). "SOX11 overexpression inhibited the invasion of colon cancer cells." (PMID 32045135, 2020). "The qPCR results showed that mimic‐miR‐223‐3p could restore the mRNA expression level of SOX11 upregulation in colon cancer cell lines after transfection with LV‐LINC00961." (PMID 32045135, 2020). "SOX11 overexpression was successfully performed in colon cancer cells." (PMID 32045135, 2020). "The study also confirmed that Sox11 could regulate the PI3K/AKT pathway in colon cancer cells." (PMID 39039706, 2024).